IL6 (interleukin 6)
Diseases named in the same sentence as IL6 in open-access papers (continued):
Sharing a sentence is not in itself a finding about the gene and the disease.
tumor (continued). "Not only these but also IL-6 and IL-1 have shown a negative impact on survival and tumor progression." (PMID 26500775, 2015). "Taken together, our data strongly suggest that IL-6 plays a pivotal role in tumorigenicity and growth of W4P-expressing cells, and estrogen is capable of suppressing W4P-LHB-mediated tumorigenicity and tumor growth." (PMID 25645622, 2015). "Our results revealed some differences in the expression of IL-6 between CAFs derived from the malignant tumor stroma and normal stromal fibroblasts derived from the nonmalignant tumor stroma." (PMID 26690480, 2015). "Interestingly, representative IHC images and quantification of IHC data of tumor tissues from the nude mice showed that sunitinib treatment increased p-PAK1, IL-6, CD73 and CD146 staining." (PMID 25675297, 2015). "However, correlating their expression with tumor severity (TNM staging system), only IL-6 and VEGF presented a positive trend with tumor progression." (PMID 25908103, 2015). "Consistently, high IL-6 synthesis by CAFs, which is also measurable in the plasma of our tumour-xenografted mouse models, is abrogated upon mouse treatment with SOM230, in correlation with enhanced tumour sensitivity to gemcitabine." (PMID 25834145, 2015). "This indicates that, in addition to its cell autonomous tumor suppressor functions, miR-146b-5p has also non-cell-autonomous activities through repressing the secretion of IL-6." (PMID 26338965, 2015). "IL-6, but not tumor necrosis factor-α, was elevated in male mice harboring W4P-induced tumor, and was reduced by estrogen." (PMID 25645622, 2015). "However, blockage of cytokine IL-6 or TNF-α signaling or inhibition of NF-κB, STAT3, or cyclinD1 expression reduced the average tumor volume (p < 0.05)." (PMID 25823926, 2015). "Moreover, concurrent expression of Oct-4 and pSTAT3 with IL-6 treatment data suggest the IL6-JAK-STAT3-Oct-4 signaling axis exist in CRC cells and contributes to tumor metastasis and invasiveness." (PMID 26258407, 2015). "In addition to promotion of angiogenesis, pro-angiogenic proteins, VEGF, IL6, and IL8, can also initiate tumor invasion and metastasis." (PMID 25970784, 2015). "Although sex did not have impact on tumour recurrence, both serum IL-6 and TNF-α were higher in men." (PMID 25858079, 2015). "Some genes in the list (e.g. IL6 and CTGF) are perhaps better known for oncogenic activity; however, they are included in the list of 830 genes because there are published reports of them demonstrating tumour suppressive behaviour in certain tissues." (PMID 26056366, 2015). "The results of this and other studies indicate that serum IL-6 is elevated in OSCC patients and may be potential marker for tumour recurrence." (PMID 25858079, 2015). "Therefore, the role of IL-6 in ASC-macrophage interaction and its role in tumor microenvironment is worth investigating more." (PMID 26317219, 2015). "Moreover, mRNA levels of inflammatory cytokines such as IL1β, IL6 and IL18 were found to be augmented in the tumor tissue after LTX-315 treatment." (PMID 26472184, 2015). "Dephosphorylation of EGFR at EGFR-Y1068 and -Y1086 sites inactivated the PI3K/Akt signaling cascade and subsequent down-regulation of downstream pro-angiogenic and -invasive proteins (VEGF, IL6, and IL8) and suppressed tumor cell proliferation, angiogenesis, and invasion." (PMID 25970784, 2015). "Anti-IL6 siRNA also reduced RFA-induced elevation in VEGF and tumor MVD (p<0.01)." (PMID 26154425, 2015). "The patients with skin GvHD stage I had either no changes in cytokine levels or only an increase of IL-6." (PMID 26315105, 2015). "To investigate whether our in vitro findings would be reflected in tumour specimens from CRC and PC, we evaluated the expression of IL6 and TGFB2 in CRC specimens (n = 14) and PC specimens (n = 12) by RT-PCR." (PMID 26503803, 2015).
tumor (continued). "Furthermore, It has been found in number of cancer models that tumor inflammatory microenvironment constitutes complement activated fragments C3, C4, and C5, Clq, and MAC, high levels of IL-6 and TGF-β." (PMID 26198107, 2015). "Adjuvant nanoparticle-encapsulated siRNA against IL-6 can be used to modulate local and regional effects of hepatic RFA to block potential unwanted pro-oncogenic effects of hepatic or renal RFA on distant tumor." (PMID 26154425, 2015). "In tumor microenvironments, MSCs can be activated by pro-inflammatory cytokines IFN-γ, TNF-α, or IL-1β, which are secreted by tumor cells and macrophages and then produce immunomodulatory molecules, such as IDO, PGE2, IL-6, IL-10, HLA-G5, and nitric oxide (NO)." (PMID 26694366, 2015). "As IL-6/STAT3 signaling can promote proliferation and survival of NSCLC cells, these data suggest that NOX4-induced IL-6 expression, at least partly, accounts for its tumor-promoting effect." (PMID 25504436, 2015). "The tumor cells express functional receptors for growth factors, cytokines, chemokines, and other molecules involved in the angiogenic and inflammatory processes including VEGF, IL-6, IL-8, CXCL12, and PTGS2 (COX-2)." (PMID 29061946, 2015). "Although the greater expression levels of STC1 in tumor samples could be interpreted as its pro-oncogenic role in tumor progression, the counteracting effects STC1 on the pro-inflammatory effects of IL6 and IL8 might slow down the process of carcinogenesis." (PMID 26469082, 2015). "Our results showed that miR-106a inhibition reduced IL-1β, IL-6, IL-8 and TGF-β production, indicating that miR-106a may contribute to tumor cell drug resistance by promoting the production of these cytokines." (PMID 25950430, 2015). "Furthermore, in tumour-bearing rats, spleen cells from CAM treated animals expressed lower levels of TGF-β and IL-6 compared to untreated animals and had a stronger tumour neutralising activity." (PMID 25729426, 2015). "MDSCs are induced by tumor-mediated inflammation, recruited to the circulation via tumor-derived factors such as IL-1, IL-6, GM-CSF, G-CSF, and VEGF, and accumulate in the tumor, tumor-draining lymph node (LN), and spleen, with MDSC numbers increasing with tumor load." (PMID 25982370, 2015). "Regardless of the stage of tumor growth, the injection of conjugates increased serum concentrations of IL-6, TNF-α, IFN-γ and IL-12p70." (PMID 26327508, 2015). "Furthermore, these cells have increased exposure to the factors necessary for tumor relapse, including CXCL12, through its receptors CXCR4 and CXCR7, IL6 through the Jak2/Stat3 pathway, EGF, FGF and IGF, among others." (PMID 25797268, 2015). "We therefore hypothesize that IL6 and CCL5 gene expression within basal cancer tumor samples may determine their metastatic potential." (PMID 26173622, 2015). "Mediators of inflammatory pathways such as interleukin-6 (IL-6), tumor necrosis factor alpha (TNFα), and cyclooxygenase-2 (COX-2) are involved in cancer-related mechanisms that diminish tumor suppressor function, stimulate oncogene expression, and increase cell cycling." (PMID 25866823, 2015). "In particular, proinflammatory cytokines, IL-1β, IL-6, and TNF-α may be released as part of the host response to the tumor or in response to tissue damage or depletion of immune cell subsets associated with cancer treatment." (PMID 25945105, 2015). "Pro-inflammatory molecules such as IL-1β, IL-6 and PGE2 are thought to promote the induction of MDSC in tumours, whereas pro-inflammatory TNF signalling can drive the accumulation of MDSC in tumours." (PMID 25738302, 2015). "Although TAMs contribute significantly to production of VEGF, IL-1β, TNF-α, IL-6, IL-23, IL-8, MMPs which have pro-angiogenic and growth attributes, specific molecular pathways in macrophages that immunoedit tumor growth are not well defined." (PMID 24842612, 2014). "CCL2, CXCL1, and IL6, produced by 18Co cells could contribute to increased STAT1 activity in tumor cells." (PMID 24818101, 2014).
tumor (continued). "First, the tumor environment can disrupt dendritic cell (DC) function of antigen-presenting cells to limit the generation of tumor reactive T cells, via transforming growth factor (TGF-β), interleukin (IL)-10, macrophage colony-stimulating factor (M-CSF), IL-6, hypoxia, and lactic acid." (PMID 24734218, 2014). "The tumor cells were positive for G-CSF, partly positive for IL-8 and weakly positive for IL-6, but negative for IL-8R/CXCR1." (PMID 25123545, 2014). "Therefore WP1066 inhibition of STAT3 activity and tumour progression was due in part to reduced polymophonuclear infiltration and reduced STAT3-dependent transcription of pro-inflammatory IL-6, IL-11, IL-1α, IL-1β and COX2 genes." (PMID 24804649, 2014). "This increases ICAM-1 expression on the tumour vasculature and tumour-specific CD8+ effector/memory T cell trafficking into the tumour, both of which are recapitulated by intravenously administering IL-6 instead of giving whole body hyperthermia." (PMID 25430985, 2014). "In this stage, the tumor-inhibiting effect of CD8+ CTLs is suppressed by FOXP3+ Tregs, myeloid suppressor cells (MDSCs), neutrophils, M2 macrophages, Th2 CD4+ T cells and cytokines such as TGF-β, IL-6." (PMID 24743335, 2014). "The increase of several immune cell-derived factors, such as interleukin-1 (IL-1), IL-6, IL-8, IL-10, and tumor necrosis factor alpha (TNF-α), has been described in tumor microenvironment: they sustain inflammatory process, contribute to tumor progression, and also exert proangiogenic activity." (PMID 24949467, 2014). "Inhibitory effects of PKCδ suppression on the IL6-Stat3 axis, which is critical for CSC genesis or maintenance in a number of tumor cells types, may also contribute to the actions of PKCδ inhibition on CSC growth and survival, and will be reported separately." (PMID 24528676, 2014). "As the expression of IL-6 and BMP-6 are elevated in the tumor microenvironment, these may be important factors in the evolution of castration resistant disease." (PMID 25333263, 2014). "Although we did not measure the G-CSF, GM-CSF, or IL-6 in the tumor cells, we compared the HE sections and several immunochemical markers in primary and recurrent tumors to investigate the possible factors related to the unusual presentation in our case." (PMID 25223869, 2014). "Like TNF-α, IL-6 facilitates tumor development by promoting conversion of noncancer cells into tumor stem cells." (PMID 24901008, 2014). "Interestingly, IRF1 depletion in tumor cells significantly attenuated BV6-stimulated secretion of IL-8, IL-6, GM-CSF and MCP-1 by tumor cells." (PMID 25501823, 2014). "Also, in cell lines of malignant fibrous histiocytoma, a high secretion of IL-6 and constitutive activation of STAT3 were reported, reflecting an increase of tumor cell proliferation." (PMID 24901008, 2014). "We then generated IL-6 transgene-engineered DC (DCIL-6) vaccine by transfection of murine bone marrow (BM)-derived ovalbumin (OVA)-pulsed DCs (DCOVA) with AdVIL-6 and further assessed DCOVA/IL-6-stimulated CTL responses and antitumor immunity in an OVA-specific animal tumor model." (PMID 24690994, 2014). "Enhanced drive for expression of IL-6 and IL-11 may also be due to increased ligand driven EGFR activation, which also signal via STAT3, and which show increased expression during active tumour growth in the gp130757FF mouse." (PMID 24804649, 2014). "However, platycodin D 200, 100 and 50 mg/kg administered mice showed significant (P < 0.01 or P < 0.05) decreases of serum IL-6 levels, and increases of IFN-γ levels as compared with tumor-bearing control, dose-dependently." (PMID 25477992, 2014). "Among tumor-derived factors that activate fibroblasts are TGFβ, PGE, TNF, IFNγ, and IL6." (PMID 24818101, 2014).
tumor (continued). "RT-qPCR analysis indicated that the expressions of the proinflammatory cytokines (TNF-α, IL-6, and IL-1β) and TLR4 of tumor tissues from group 2 were markedly increased at mRNA level after LPS treatment, compared with those of group 1 or 3 without LPS treatment." (PMID 25179302, 2014). "The formation of this inflammatory outer zone around the tumor was likely not due to the production by tumor cells of IL-6 or G-CSF." (PMID 25123545, 2014). "Interestingly, the Akt/PI3K/mTOR cascade mediates signalling from leptin and IL-6, which in our have been shown to be significantly elevated in EDBC patients and positively correlated with tumour stage." (PMID 25338520, 2014). "Stress inhibits the immune response ability in antigen-specific T-cells and natural killer cells while stimulates the secretion of proinflammatory cytokines, such as IL-1, IL-2, IL-6, IL-8, IL-11 and TNF-α, which were regarded as co-factors for modulating the growth and progression of tumor." (PMID 24555849, 2014). "However, in epithelial cell lines, miR-21 is activated by IL-6 and STAT3 and targets PTEN, which leads to increased NF-κB activity and tumour growth." (PMID 25598707, 2014). "IL-1β released by stromal cells together with other tumor-derived factors, including granulocyte macrophage colony-stimulating factor (GM-CSF), cyclooxygenase 2 (COX-2), IL-6, and VEGF, induce the accumulation and expansion of MDSCs by triggering Janus kinase (JAK)/STAT3 pathways." (PMID 25136593, 2014). "Inflammatory cytokines such as interleukin-6 (IL-6), tumor necrosis factor alpha (TNF-α), and interleukin-1 beta (IL-1β) produced by the tumor or adipose tissue may also contribute to adipose depletion." (PMID 25415607, 2014). "Interestingly, ISG15 silencing affected tumor microenvironment including MVD and cytokines such as VEGF and IL-6." (PMID 25238261, 2014). "The tumor-promoting feature of Th17 cells largely arises from secretion of large amounts of IL-17, which in turn induces expression of pro-inflammatory factors such as TNF-α, IL-6, IL-1, and iNOS, known to play a role in CRC pathogenesis." (PMID 24639678, 2014). "In the present study, the predominance of cytokine secretion between tumor and stroma is not evident, and a role for IL6 as another mediator cannot be excluded." (PMID 24885802, 2014). "To further investigate whether ISG15 affects the tumor microenvironment, we detected microvessel density (MVD) and cytokines such as vascular endothelial growth factor (VEGF) and Interleukin-6 (IL-6) in mouse models of HCC." (PMID 25238261, 2014). "fibroblast or epithelium; Fourth, multiple DDSP proteins are well-known to promote disease evolution particularly tumor progression, including proteases (MMPs), growth factors (AREG, EREG), pro-angiogenic factors (ANGPTL4, VEGF), and pro-inflammatory cytokines (IL-6, IL-8)." (PMID 25185441, 2014). "Accordingly, irradiation-induced IL-6 and TGF-β could act separately as a pro-tumor factor as well as accelerated tumor growth through the induction of IL-17A in this study." (PMID 25181290, 2014). "Interestingly, levels of both IL-6 and TNF-α level was found to be substantially higher in untreated tumor bearing mice." (PMID 24504138, 2014). "It is reported that PRDX1 could be secreted from tumor cells and extracellular PRDX1 could induce the secretion of proinflammatory cytokines such as TNF-α and IL-6." (PMID 25024510, 2014). "IL-6 was overexpressed in tumor tissues compared to adjacent non-malignant epithelial tissues, and this expression was significantly associated with poorer treatment response rates, shorter survival, and the development of distant metastases." (PMID 25268165, 2014). "Both, tumor and host cells produce different mediators, for example, C-reactive protein (CRP), proinflammatory cytokines with tumor necrosis factor-α (TNF-α), interleukin-6 (IL-6), interferon-γ (IFN-γ), and adipocytokines." (PMID 25049439, 2014).
tumor (continued). "Cellular IL-6, a bridge molecule between chronic inflammation and carcinogenesis, could promote colonic tumorigenesis through DNMT1-mediated tumor suppressor gene hypermethylation." (PMID 24675762, 2014). "The microenvironment of tumours are typically rich in proinflammatory mediators, such as Tumour Necrosis Factor (TNF)-α, Interleukin (IL)-1, IL-6, IL-8, cyclooxygenases-2 (COX-2), and inducible nitrogen synthesis (iNOS) which are essential components of the tumour initiation and promotion." (PMID 24734105, 2014). "Presumably, one part of these IL-6 effects is achieved by increasing TWIST-expression, as well as stabilizing TWIST and inhibiting its degradation, thereby increasing cell motility and tumor progression." (PMID 24887580, 2014). "CAFs promote tumor growth and invasion secreting proangiogenic factors (i.e., VEGF-A and MMP-9), proinflammatory molecules (i.e., SDF-1, IL-6, and IL-1β), and several growth factors (i.e., TGF-β, platelet-derived growth factor, PDGF, and basic fibroblast growth factor, bFGF)." (PMID 25136593, 2014). "An earlier study demonstrated that IL6 is accountable for a higher incident rate of HCC in males than in females in a mouse model, suggesting that higher IL6 expression and the subsequent activation of STAT3 in surrounding liver “prime” events for tumor development." (PMID 25536056, 2014). "IL-6 may also decrease HCC cell apoptosis, thus conferring a survival advantage to the tumor; indeed, in a mouse model, IL-6 proved to reduce Fas-induced apoptosis." (PMID 27335826, 2013). "Interestingly, IL-6, IL-8 and GRO, are involved in tumour aggressivity by favoring a higher invasiveness potential of cancer cells and a proangiogenic activity." (PMID 23388133, 2013). "Furthermore, when mice were irradiated with a sub-lethal dose, inhibition of IL-6 protein expression attenuated angiogenesis, MDSC recruitment, and decreased tumor regrowth." (PMID 23806095, 2013). "Taken together with the increased IL-6 levels only in the vicinity of metastasizing tumor cells, these findings suggest that IL-6 trans-signaling occurs preferentially in primary tumor sites and the metastatic lung but not in the spleen." (PMID 24021059, 2013). "Tumor cells disturb the balance of osteoblast and osteoclast activity by secretion of bone-active regulatory factors such as endothelin-1 (ET1), interleukin-6 (IL6) and transforming growth factor β (TGFβ) in order to enhance bone turnover and release of nutrients and growth factors." (PMID 23792785, 2013). "However, these cells, although intended to help promote tumor clearing, can inadvertently aid in the promotion and expansion of tumor growth through secreted cytokines including TNF-α and IL-6." (PMID 24244348, 2013). "It further supports that IL-19 not only directly facilitates cell proliferation, cell migration, and metastasis but it also prompts the expression of IL-1β, IL-6, TGF-β, MMP-2, MMP9, CXCR4, and fibronectin, which supply of a microenvironment for tumor growth and metastasis." (PMID 23710200, 2013). "In the primary tumor, the IL-6 production in mMDSC was significantly reduced by curcumin compared to Listeriaat-Mage-b, but IL-6 was not produced by gMDSC." (PMID 24156030, 2013). "High levels of IL-6 and IL-10 are observed in HCC patients, correlate with tumor size, and may be helpful to identify a subset of HCC patients with low AFP level." (PMID 27335826, 2013). "Different markers present not only in the tumour cells, but also in the tumour microenvironment and released in blood such as IL6, not only present the potential to predict prognosis, but also offer new potential target therapies to improve therapy efficacy." (PMID 23837802, 2013). "Many tumor-derived factors, such as IL-10, IL-6 and VEGF that are crucial for both tumor growth and immunosuppression, activate STAT3 to create an efficient “feed-forward” loop to induce persistent STAT3 activity in tumor cells and the tumor microenvironment." (PMID 24324713, 2013).